MAX (MYC associated transcriptional regulator X)
Description:
Transcription regulator. Forms a sequence-specific DNA-binding protein complex with MYC or MAD which recognizes the core sequence 5'-CAC[GA]TG-3'. The MYC:MAX complex is a transcriptional activator, whereas the MAD:MAX complex is a repressor. May repress transcription via the recruitment of a chromatin remodeling complex containing H3 'Lys-9' histone methyltransferase activity. Represses MYC transcriptional activity from E-box elements.
Synonyms: bHLHd4; bHLHd5; bHLHd6; bHLHd7; bHLHd8; PDMCS
Tractability: Small molecule: a structure with a bound ligand is known; a high-quality ligand is known. PROTAC: ubiquitination databases record sites on it; its protein half-life has been measured; a small molecule that binds it is known.
Target class: Transcription factor
Gene: Protein-coding gene on chromosome 14 (65,006,174 to 65,102,695, reverse strand). Ensembl gene ENSG00000125952.
Subcellular location: Nucleus; Cell projection, dendrite
Subcellular location (Human Protein Atlas): Nucleoplasm; Golgi apparatus
Pathways (Reactome):
Cell Cycle: Cyclin A:Cdk2-associated events at S phase entry; Cyclin E associated events during G1/S transition; Transcription of E2F targets under negative control by DREAM complex
Gene expression (Transcription): Transcriptional Regulation by E2F6
Gene Ontology:
Molecular function: DNA binding; DNA-binding transcription factor activity, RNA polymerase II-specific; DNA-binding transcription factor binding; DNA-binding transcription repressor activity, RNA polymerase II-specific; E-box binding; identical protein binding; protein binding; RNA polymerase II transcription regulatory region sequence-specific DNA binding; sequence-specific double-stranded DNA binding; DNA-binding transcription factor activity; protein dimerization activity; RNA polymerase II cis-regulatory region sequence-specific DNA binding
Biological process: negative regulation of transcription by RNA polymerase II; positive regulation of DNA-templated transcription; regulation of transcription by RNA polymerase II; heterochromatin formation; negative regulation of DNA-templated transcription; positive regulation of transcription by RNA polymerase II
Cellular component: chromatin; Mad-Max complex; MLL1 complex; Myc-Max complex; nucleoplasm; nucleus; protein-DNA complex; RNA polymerase II transcription regulator complex; RNA polymerase II transcription repressor complex; PRC1 complex; dendrite
Genetic constraint (gnomAD): Loss-of-function variants: 1 observed, 16.5 expected, observed/expected ratio (o/e) 0.0606, 90% interval 0.021 to 0.29. The upper end of that interval is the gene's LOEUF score, 0.29, which puts it in group 1 of 6, group 1 being the genes least tolerant of losing a copy. Missense variants: 103 observed, 169.61 expected, observed/expected ratio (o/e) 0.61, 90% interval 0.52 to 0.71. Synonymous variants: 54 observed, 65.88 expected, observed/expected ratio (o/e) 0.82, 90% interval 0.66 to 1.03.
Gene-disease validity (ClinGen):
ClinGen rates the evidence that MAX causes each of these diseases.
hereditary pheochromocytoma-paraganglioma (autosomal dominant): Definitive. Neoplasm predisposition characterized by an increased risk of paragangliomas (tumors that arise from neuroendocrine tissues distributed along the paravertebral axis from the base of the skull to the pelvis) and pheochromocytomas (paragangliomas that are confined to the adrenal medulla).
Cancer hallmarks: escaping programmed cell death (promotes); suppression of growth (promotes); invasion and metastasis (promotes); proliferative signalling (promotes); escaping programmed cell death (suppresses)
Homologues: Orthologues: dog MAX (100% identical), macaque MAX (100% identical), mouse Max (99% identical), guinea pig MAX (99% identical), rabbit MAX (98% identical), pig MAX (94% identical), chimpanzee MAX (90% identical), rat Max (88% identical), zebrafish max (85% identical), tropical clawed frog max (72% identical), Drosophila melanogaster Max (46% identical), Caenorhabditis elegans mxl-3 (41% identical), and 1 more.
Diseases named in the same sentence as MAX in open-access papers:
MAX is named in the same sentence as 128 diseases in open-access papers, as found by Europe PMC text mining. Sharing a sentence is not in itself a finding about the gene and the disease. The quoted sentences say what the papers report.
pheochromocytoma (45 papers, 2013 to 2025). "The aim of this study was to investigate the genotypic and clinical phenotypic characteristics of MAX germline mutation–associated pheochromocytoma (PCC) and paraganglioma (PGL)." (PMID 39279998, 2024). "For example, germline MAX mutations are associated with neuroendocrine tumors including prolactinomas and pheochromocytomas." (PMID 37104368, 2023). "Here, we report a case of bilateral pheochromocytoma (PCC) with a variant in the MYC-associated factor X (MAX) gene (c.295 + 1G > A)." (PMID 35645312, 2022). "We report a family with hereditary pheochromocytoma carrying a MAX deleterious variant in four affected relatives." (PMID 33815275, 2021). "We describe a deleterious MAX variant associated with hereditary pheochromocytoma in a family with four affected individuals." (PMID 33815275, 2021). "Germline variants of the MYC-associated factor (MAX) gene have been associated with familial pheochromocytomas and paragangliomas with an autosomal dominant pattern of inheritance, a median age at onset of 33 years and an overall frequency estimated at 1.9%." (PMID 33815275, 2021). "This case series is, to our knowledge, the one with the largest number of individuals with hereditary pheochromocytoma with a deleterious MAX variant in the same family." (PMID 33815275, 2021). "A rare clinical situation of acromegaly due to ectopic GHRH production by PPGL (usually phaeochromocytoma) has also been described, including a MAX mutation positive case." (PMID 33805450, 2021). "Phaeochromocytoma/paraganglioma can be associated with pituitary tumours (the 3Pa), even carcinoma, due to mutations in SDHx or MAX genes." (PMID 33543431, 2021). "It is also the first case with a synchronous pheochromocytoma and neuroblastoma in carriers of a MAX deleterious variant." (PMID 33815275, 2021). "A number of CPGs in which variants were identified, such as MAX and FH, have been relatively recently described as causing pheochromocytoma and paraganglioma." (PMID 29909963, 2018). "This research also showed that somatic mutations in MAX occurred in 1.65% of paragangliomas/pheochromocytomas but that only 7% of mutations in the MAX gene resulted in metastasis." (PMID 28187001, 2017). "A number of genomic sequencing studies have identified inactivating MAX mutations and deletions in human pheochromocytomas, small-cell lung tumors, and oligodendroglial tumors." (PMID 28587062, 2017). "We experienced a case of synchronous bilateral pheochromocytomas and paraganglioma with novel MYC associated factor X (MAX) gene mutation." (PMID 29282558, 2017). "Overall, the results of analysis of 2041 cases of paragangliomas/pheochromocytomas with mutations in the MAX gene are presently available in the literature." (PMID 28187001, 2017). "Here, we report the case of synchronous bilateral pheochromocytomas and paraganglioma with novel MYC associated factor X (MAX) gene mutation." (PMID 29282558, 2017). "The only currently known association with MAX and tumor biology in humans comes from studies of pheochromocytoma and paraganglioma patients." (PMID 24349289, 2013). "Another pheochromocytoma-susceptible gene is MYC-associated factor X (MAX)." (PMID 40649858, 2025). "In hereditary pheochromocytoma additional MAX mutations were found, however." (PMID 34689785, 2021). "For the individual with FH and MAX variants, it is easier to attribute the diagnosed pheochromocytomas to the truncating MAX variant, but evidence for the role of FH in this tumor type is accumulating, and this variant could have contributed to tumorigenesis." (PMID 29909963, 2018). "Both somatic and germline mutations in the MAX gene have been detected in pheochromocytomas." (PMID 28187001, 2017). "Notably, although the interaction of MAX and MYC is considered to be activating, mutations in the MAX gene resulting in pheochromocytomas involve loss of function of this protein, whereas the activity of MYC in tumors is elevated." (PMID 28187001, 2017).
pheochromocytoma (continued). "Therefore, mutations in the MAX gene should be sought in patients with familial, bilateral or apparently sporadic phaeochromocytoma/paraganglioma." (PMID 29166454, 2017). "Although the mechanism in which a MAX mutation causes phaeochromocytoma remains unclear, recent studies show that partial deletion and reintroduction of MAX results in cell growth arrest supporting the role of MAX repressing the oncogenic effects of MYC on paraganglial cells." (PMID 29166454, 2017). "MAX is involved in cell proliferation and differentiation and germline PVs in MAX have been reported in relation to pheochromocytoma development." (PMID 39979679, 2025). "The VUS identified in MAX has previously also been identified in a male who developed a pheochromocytoma and a pituitary adenoma." (PMID 39979679, 2025). "On the other hand, several patients have been reported with a MAX pathogenic or likely pathogenic variant and a NET other than pheochromocytoma in the literature." (PMID 39398337, 2024). "The concurrence of pheochromocytoma and MTC among the familial AMH cases supports a genetic association between familial pheochromocytoma and MTC with RET, SDHD, MAX, and NF1 pathological variants being reported." (PMID 36896586, 2023). "AMH can be sporadic or familial, resulting from germline mutations of genes known to cause pheochromocytoma, such as the RET gene in multiple endocrine neoplasia type 2 (MEN2) syndrome, or in the NF1, SDHB, and MAX genes." (PMID 36896586, 2023). "Of the 12 familial cases of pheochromocytoma, 9 were associated with MEN 2, 2 with NF1 and 1 with MAX pathological variants." (PMID 36896586, 2023). "Cluster 2 PPGLs are built-up mostly by pheochromocytomas driven by variants in genes regulating kinase-driven pathways, including NF1, KIF1B, MAX, RET, TMEM127 and H-RAS." (PMID 35205664, 2022). "MAX is the associated factor X of MYC (MAX and MYC together form a protein complex that is a transcriptional activator) and is associated with pheochromocytoma." (PMID 35428183, 2022). "A similar case has now been described in a patient with germline MAX mutation and multiple tumours including a GHRH-positive phaeochromocytoma." (PMID 33543431, 2021). "It has been reported that MAX mutations are involved in the pathogenesis of hereditary pheochromocytoma (PCC)/paraganglioma (PGL), but MAX mutations mainly cause PCC." (PMID 32973681, 2020). "An alternate explanation can be found in studies that show MYC can function independently of MAX in pheochromocytoma and small cell lung cancer." (PMID 31156714, 2019). "In contrast, silencing MAX in pheochromocytoma cells that express PNMT results in attenuated steroid-induced PNMT." (PMID 31390824, 2019). "VHL, RET, NF1, SDHB, and SDHD are major susceptibility genes, accounting for 90% of familial pheochromocytomas/paragangliomas, whereas TMEM127, SDHA, SDHC, SDHAF2, and MAX are minor susceptibility genes responsible for 10% of these tumors." (PMID 30456751, 2018). "In face of the malignant presentation, molecular studies were conducted to screen mutations in five genes related to pheochromocytoma: SDHB, SDHD, SDHC, MAX and VHL." (PMID 29768630, 2018). "Inactivating MAX mutations have recently been reported in inherited and sporadic PGL and pheochromocytomas (PCC), and in small cell lung cancer (SCLC) specimens." (PMID 26555092, 2015). "More recently, the TMEM127, MAX, HIF2A, EGLN1, KIF1B, and H-RAS complete the list of susceptibility genes implicated in the development of paragangliomas/pheochromocytomas." (PMID 24899893, 2014). "Furthermore, some gene mutations, such as those impacting the myc-associated factor X (MAX) gene, can predispose to both childhood neuroblastoma and pheochromocytoma." (PMID 35957826, 2022). "However, MAX is deleted in some cancers, as pheochromocytoma, paraganglioma, gastrointestinal stromal tumors, and small cell lung cancer." (PMID 33419981, 2021).
pheochromocytoma (continued). "Recently MAX mutation has been described in families with phaeochromocytoma, pituitary adenoma and other endocrine- and non-endocrine tumours." (PMID 33543431, 2021). "Germline VHL, SDHx and FH mutations may predispose to phaeochromocytoma/paraganglioma and RCC, and on rare occasions renal tumours have been reported in association with mutations in the phaeochromocytoma genes TMEM127 and MAX." (PMID 29680948, 2018). "The basis of some of these treatment options is based on the discovery of a number of genes associated with pheochromocytomas, including neurofibromin 1 (NFI), von Hippel-Lindau (VHL), transmembrane 127 (TMEM127), proto-oncogene (RET), and MYC associated factor X (MAX)." (PMID 23785438, 2013). "The MAX R60Q mutation had a frequency of 0.9%, slightly lower than reported before (1.7%) and it was the only relevant alteration to be found in the MAX coding region, unlike in pheochromocytoma." (PMID 34689785, 2021). "Thus, mutations in the MAX gene appear to be rare and are unlikely to be associated with elevated tumor aggressiveness, making them unsuitable as targets of genetic screening for paragangliomas/pheochromocytomas." (PMID 28187001, 2017). "MYC requires its basic helix-loop-helix leucine zipper (bHLHLZ) dimerization partner MAX for its transcriptional and oncogenic activities however, a rat pheochromocytoma cell line (PC-12) does not express MAX mRNA or protein, yet retains a transcriptionally functional MYC protein." (PMID 28587062, 2017). "In a study of 972 cases from the European-American-Asian Pheochromocytoma and Paraganglioma Registry without mutations in the common PPGL genes, 58 had mutations in less commonly mutated genes (SDHA, TMEM127, SDHAF2) including 8 cases of PCC with MAX mutations." (PMID 31666924, 2019).
paraganglioma (24 papers, 2013 to 2025). A benign or malignant neoplasm arising from paraganglia located along the sympathetic or parasympathetic nerves. "For example, we identified in the HMF breast metastasis series significantly recurrent mutations of CDKN1A (known driver in bladder cancer), MAX (known in paragangliomas, endometrioid and colon carcinomas) and CDK12 (known in ovarian cancer)." (PMID 36937541, 2023). "Sporadic panNETs arose in 141 patients with panNET-associated familial syndromes in 42 individuals: 36 with MEN1, 2 with VHL, 1 each with TSC, NF1, paraganglioma, MAX mutation and MUTYH-associated polyposis." (PMID 34163434, 2021). "Furthermore, the participation of menin in c-Jun activation and its suppression by the MYC protein suggest that mutations in MEN1 and MAX may play a certain role in paraganglioma development." (PMID 28187001, 2017). "In addition, although the exact mechanism by which mutations in MAX lead to paraganglioma development is unknown, these tumors exhibit an elevated expression of the MYC target genes." (PMID 28187001, 2017). "The prevalence of germline mutations in SDHB, SDHC, SDHD, VHL and MAX in PCC and paraganglioma patients is, respectively, 10%, 1%, 9%, 7%, and 1%." (PMID 29768630, 2018). "Recently, other genes (TMEM127, MAX, HIF2A, EGLN1, KIF1B, H-RAS) have been added to the group of susceptibility genes involved in the development of paragangliomas/PHEO." (PMID 26084817, 2015). "SDHA, SDHAF2, SDHB, SDHC, SDHD, MAX, and TMEM127 genes are offered to be analyzed for the diagnosis of paraganglioma/pheochromocytoma (PGL/PCC) syndromes." (PMID 33777662, 2021). "We could not include other paraganglioma genes like SDHA, SDHC, MAX, etc., and we did not include NF1 carrier cases in this study." (PMID 33777662, 2021).
neuroblastoma (21 papers, 2013 to 2025). Neuroblastoma (NB) is the most common solid, extracranial childhood tumor. "In conclusion, we describe a family with a MAX variant associated with hereditary PPGL with one of the patients presenting with a bilateral PPGL with synchronous neuroblastoma, the first case reported to our knowledge." (PMID 33815275, 2021). "Our case is, to the best of our knowledge, the first with a simultaneous PPGL and neuroblastoma presenting as two distinct entities in association with a MAX pathogenic variant." (PMID 33815275, 2021). "Curiously, this cells are MYCN amplified, suggesting that MAX expression is sufficient to revert proliferation even in more aggressive neuroblastoma cell variants." (PMID 24349289, 2013). "Whether MAX mutations can cause neuroblastoma is still uncertain." (PMID 32973681, 2020). "For example, a variant in MAX, an essential interacting partner of MYC, was identified in a patient with neuroblastoma." (PMID 30455982, 2018). "MYC/MAX/MXD1 network has been shown to play a major role in the development of neuroblastoma and melanoma." (PMID 29383100, 2017). "We have also found that MAX expression and protein levels were increased during neuroblastoma SH-SY5Y cells differentiation." (PMID 24349289, 2013). "We have found an increased amount of MAX after the 4th day of experiment, demonstrating that the changes in mRNA expression are indeed reflected at protein level in neuroblastoma cells." (PMID 24349289, 2013). "We propose that MAX is involved in neuroblastoma progression, possibly increasing cell differentiation by means of regulating the availability of MYC:MAX heterodimers." (PMID 24349289, 2013). "Corroborating this data, we have analyzed a survival cohort of neuroblastoma patients and found that individuals with lower MAX expression had significantly decreased survival rates than the others." (PMID 24349289, 2013). "We have previously shown that high-level MAX expression in MYCN-amplified primary neuroblastomas confers a poor outcome, while knockdown of MAX in MYCN-amplified cell lines inhibits both cell growth and motility, suggesting that MAX has a critical role in MYCN-mediated oncogenesis." (PMID 38992040, 2024). "This suggests that all MAX germline mutation carriers should receive a comprehensive baseline assessment of the diversity of neurocrest-derived diseases, such as PPGL, PA, hyperparathyroidism, and ganglioneuroma/neuroblastoma." (PMID 39279998, 2024). "In addition, the function of MYCN/MAX and C-Myc/MAX heterodimers as global transcriptional amplifiers regulated by super-enhancer elements likely also plays a major role in neuroblastoma development." (PMID 29755654, 2018). "Additionally, the HIFs have also been shown to interact directly with the MYCN/MAX complex in neuroblastoma, which has a complex effect on cellular phenotype." (PMID 27765905, 2016). "Therefore, binding partners other than MAX are likely more relevant to driving MYCN-mediated poor neuroblastoma outcome." (PMID 26673823, 2015). "Our analysis pointed MAX as one of the MRs of neuroblastoma progression." (PMID 24349289, 2013). "The relative expression ratio of MAX to MYCN is a key factor in disease progression and clinical prognosis: a higher MAX/MYCN ratio can inhibit the oncogenic effects of MYCN and improve neuroblastoma prognosis." (PMID 41244073, 2025). "Dysregulation of the MAX–MYC pathway can lead to the development of many tumors, including neuroblastoma." (PMID 32973681, 2020). "MYCMI-6 has GI50s as low as 0.5 μM in neuroblastoma and Burkitt’s lymphoma cells with deregulated MYCN/MYC, which is much more potent in comparison to most of the previously reported MYC:MAX inhibitors, such as 10058-F4, 10058-F4 analogues and 10074-G5." (PMID 29968736, 2018). "In contrast, the expression of MAX was not affected in these cell lines, except in Kelly neuroblastoma cells where MAX protein level was reduced following treatment with MYCMI-7." (PMID 36874405, 2022).